GZMK (granzyme K)
Diseases named in the same sentence as GZMK in open-access papers (continued):
Sharing a sentence is not in itself a finding about the gene and the disease.
IgG4-related disease (1 paper, 2025). "Given that TFR cells have been implicated in suppressing GZMK+ cytotoxic TFH cells in ectopic lymphoid follicles of patients with IgG4-related disease, we assessed the ratio of GZMK+TIA-1+ or GZMB+TIA-1+ TFK cells to TFR cells." (PMID 41030456, 2025).
ischemic stroke (1 paper, 2025). A stroke disorder caused by obstruction of blood flow to the brain, due to thrombotic (local blood clot formation) or embolic (due to a blood clot or other material traveling from another site) event. "These analyses underscore the distinctive characteristics of different GZMK+ T-cell subsets, emphasizing that CD8+ GZMK+ T cells, rather than CD4+ GZMK+ T cells, are associated with ischemic stroke and reperfusion." (PMID 40659887, 2025).
liver cancer (1 paper, 2022). An epithelial or non-epithelial malignant neoplasm that arises from the liver. "An analysis of single-cell sequencing data of liver cancer immune cells found that lncRNA MIAT was significantly enriched in Foxp3+ CD4+ T cells, PDCD1+ CD8+ and GZMK+ CD8+ T cells, which mediated the immune escape of liver cancer." (PMID 36092924, 2022).
myocarditis (1 paper, 2025). Myocarditis is a condition that is characterized by inflammation of the heart muscle (myocardium). "TCR sequencing revealed expansions of CD8 GZMK + GZMA + and CD8 PRF1 + GZMA + T cells in myocarditis patients, along with increased activation markers CD69 and KLRG1, supporting the idea that specific cytotoxic CD8 T cell groups promote inflammation." (PMID 41510228, 2025).
myxoma (1 paper, 2024). A benign soft tissue neoplasm characterized by the presence of spindle and stellate cells, lobulated growth pattern, and myxoid stroma formation. "Immune cells surrounding the myxoma displayed suppressive characteristics, potentially contributing to the tumor’s strategy of evading immunity, as evidenced by the impaired effector function of CD8 + T cells expressing GZMK and TOX highly." (PMID 39090109, 2024). "The mIHC experiments revealed that compared to normal tissue, myxoma exhibited a higher proportion of CD8 + T cells expressing TOX and higher expression levels of GZMK while showing lower expression levels of GZMB, which confirmed the characteristic dysfunction of CD8 + T cells in myxoma." (PMID 39090109, 2024).
Obesity (1 paper, 2024). Accumulation of substantial excess body fat. "Interestingly, GZMK+T cells in obese tumor samples showed a lower cytotoxic expression pattern compared to those in non-obese tumor samples, which suggests that obesity may impact the cytotoxic function of GZMK+T cells in CRC." (PMID 38311726, 2024).
osteoarthritis (1 paper, 2025). A noninflammatory degenerative joint disease occurring chiefly in older persons, characterized by degeneration of the articular cartilage, hypertrophy of bone at the margins and changes in the synovial membrane. "GzmK+CD8+T cells, by secreting GzmK, also inhibit osteoclastogenesis in postmenopausal osteoarthritis (OA) via activating the p38 mitogen-activated protein kinase (MAPK) signaling pathway." (PMID 41009359, 2025).
Peri-Implantitis (1 paper, 2022). An inflammatory process with loss of supporting bone in the tissues surrounding functioning DENTAL IMPLANTS. "MAPT, GZMK, and SOSTDC1 were highly correlated with high abundance of immune cells, possibly reflecting immune cell perturbations accompany ageing-associated signalling pathways to play a role in peri-implantitis lesions in aged tissues." (PMID 36267464, 2022).
placental abruption (1 paper, 2024). Vaginal bleeding preceding the 20th week of gestation. "Increased placental GZMK expression has been observed in cases of placental abruption, leading to severe bleeding during pregnancy." (PMID 38672196, 2024).
preeclampsia (1 paper, 2024). Preeclampsia is a hypertensive disorder of pregnancy that is characterized by new-onset hypertension with proteinuria presenting after 20 weeks of gestation, and depending on mild or severe forms may initially present with severe headache, visual disturbances, and hyperreflexia. "The strong expression of GZMK and mild expression of FasL were observed in extravillous trophoblasts in the placenta with preeclampsia, while GZMK expression was mild and FasL expression was moderate in extravillous trophoblast cells in the control placenta." (PMID 38672196, 2024). "We observed differences in the intensity and distribution of staining for GZMK, FasL and IFN-γ in preeclampsia and the control placenta." (PMID 38672196, 2024).
rheumatic disorder (1 paper, 2024). Inflammatory and degenerative diseases of connective tissue structures, such as arthritis. "While increasing numbers of studies have reported the expansion of GzmK-expressing CD8+ T cell populations in rheumatic disorders, the recognized role of extracellular GzmK in RA is currently restricted to pro-inflammatory cytokine production." (PMID 39475853, 2024).
scoliosis (1 paper, 2012). A congenital or acquired spinal deformity characterized by lateral curvature of the spine. "In patients with elbow contractures and scoliosis (sideways curving of the spine), an up-regulation of three inflammatory genes was found when compared with patients without those features, namely HLA-DRB1 and HLA-DRB5, (FC = 8.8, 7.1), and GZMK (FC = 1.3; FDR = 0%)." (PMID 22479353, 2012).
Stroke (1 paper, 2025). Sudden impairment of blood flow to a part of the brain due to occlusion or rupture of an artery to the brain. "We further verified whether the proportions of GZMK+ T cells were associated with stroke outcome." (PMID 40659887, 2025). "We identified a previously unrecognized GZMK+CD8+CD27+CCR7+ T-cell subset in AIS patients, named stroke-associated T (Tsa) cells, which was significantly positively correlated with the severity of clinical symptoms." (PMID 40659887, 2025). "Through single-cell RNA sequencing, we identified a novel GZMK+CD8+CD27+CCR7+ T-cell subset in patients with acute ischemic stroke (AIS), which we designated stroke-associated T (Tsa) cells." (PMID 40659887, 2025). "Flow cytometry analysis revealed that before treatment, the proportions of both CD4+ GZMK+ and CD8+ GZMK+ T cells were greater in the PBMCs of AIS patients than in those of non-stroke controls." (PMID 40659887, 2025).
systemic juvenile idiopathic arthritis (1 paper, 2022). "In contrast, in systemic juvenile idiopathic arthritis, CD56(bright) NK cells have decreased granzyme K expression and IL-18-driven IFN-γ production, which demonstrated the multi-function role of NK cells in autoimmune arthritis." (PMID 35432322, 2022).
typhoid fever (1 paper, 2017). A bacterial infectious disorder contracted by consumption of food or drink contaminated with Salmonella typhi. "Peripheral blood mononuclear cells of typhoid fever patients had a higher percentage of lymphocytic cells expressing intracellular granzyme A and granzyme B, but not granzyme K, compared to controls." (PMID 28749963, 2017). "We also measured the cells expressing granzyme K, which is thought to stimulate monocytic cells to secrete pro-inflammatory mediators like granzyme A, and this was increased in typhoid fever patients albeit not statistically significantly." (PMID 28749963, 2017).
tumor (128 papers, 2015 to 2026). "GZMK is known to play immunosuppressive roles, potentially also activating tumor-associated M2 macrophages." (PMID 40075642, 2025). "Statistical analysis showed significant differences in GZMK expression levels associated with tumor differentiation and lymph node staging (P < 0.05)." (PMID 38833021, 2024). "Of note, tumor TEX (T10) clones linked to ascites-derived GZMK+ TEM showed mutually exclusive patterns with tumor T10 clones linked to T07 and T08 clusters in tumors." (PMID 37488416, 2023). "We previously reported that anti-VEGF lenvatinib effectively recruits GZMK+ CD8 T cells to the tumor site through CXCL9 released from tumor-associated macrophages; however, it also enriched intratumoral stroma by upregulating fibrosis-related pathways." (PMID 37894439, 2023). "Here the authors show that tumor infiltrating neutrophils expressing high levels of CD15 interact with CD8+ T effector memory skewing them to produce GZMK, associated with tumor progression in CRC patients." (PMID 36347862, 2022). "Several studies have also revealed the association of LAYN, CTLA4, and GZMK expression with tumor-infiltrating exhausted CD8+ T cells and a poor prognosis." (PMID 35854246, 2022). "GZMK, a granzyme family member, has been implicated in immune surveillance and tumor cell killing." (PMID 40332815, 2025). "Moreover, while the frequency of GZMK−.C3–9.DN-Tem was associated with age, the frequency of GZMK+.C3–9.DN-Tem was dependent on tumor stage." (PMID 40307573, 2025). "However, GZMK+ CD8+ T‐cells have been observed within tumor stroma and have been implicated in poor prognosis." (PMID 39529512, 2025). "Furthermore, we observed that granzyme K (GZMK), which is recognized as a hallmark of cellular immune aging, is upregulated in peri-tumor specimens." (PMID 39944754, 2024). "Notably, tumor regression also associated with a significantly increased CD4 subset expressing Granzyme K (FC3-GZMK)." (PMID 37185301, 2023). "Clonal analysis of tumor-emergent T cells post-treatment revealed granzyme K (GZMK) expression within differentiated subsets as a marker of recent differentiation." (PMID 42000944, 2026). "These cytotoxic CD4+ T cells express granzyme K and granzyme B and exhibit the ability to kill autologous tumor cells in an MHC-II-dependent fashion, suggesting a direct role in tumor destruction." (PMID 40177538, 2025). "In contrast, basal proliferation of GZMK+CD4+ T cells in the periphery before treatment in patients with cancer suggests chronic activation stemming from the presence of tumor." (PMID 40299576, 2025). "There were four major clusters of non-PIT-1 tumor cells, and of the three clusters with majority TPIT-lineage tumor cells, one had significantly elevated Granzyme K (GZMK) expression, suggesting a possible novel subtype of corticotroph tumor." (PMID 40959438, 2025). "While CD8A expression was higher in fetal‐type tumours, GZMK and SLC4A10 were more highly expressed in embryonal‐type tumours." (PMID 40099956, 2025). "This study explored the role of perforin-1 (PRF1) and granzymes A, B and K (GZMA, GZMB and GZMK) in cancer biology, focusing on their impact on tumor cell death and immune response modulation." (PMID 40002821, 2025). "The reduction of tumor‐killing GZMK+CD8+ Tem cells and the accumulation of tumor‐resident ZNF683+CD8+ Trm cells indicate substantial remodelling of CD8+ T cell populations in ICB‐resistant RCC, of which the driving factors require in‐depth investigation." (PMID 41117057, 2025). "BayeSpace‐enhanced spatial data revealed the abundant infiltration of T cells (CD3D, IL7R), B cells (MS4A1, MZB1), and cytotoxicity markers (GZMK) throughout tumor sections of HT samples, presenting an “immune‐activation” TME after HAIC therapy." (PMID 39686623, 2025). "Significant enrichment in tumor-blood matched TCR clusters was also seen in cytotoxic CD8+ (GZMK+, GZMB+, and MAIT) T cells." (PMID 40299576, 2025).
tumor (continued). "Infiltrated CD8+ T cells are GZMK+ precursor-exhausted cells that have lost their capacity to kill tumor cells." (PMID 38460015, 2024). "GZMK+ CD8+ T cells have been reported to regulate intestinal epithelium cells in response to neutrophil activation in tumours, and our data are consistent with them adopting a primarily non‐cytotoxic role." (PMID 38707998, 2024). "Our findings revealed that GZMK+T cells in obese tumor samples have a lower glycolytic metabolic score compared to those in non-obese tumor samples." (PMID 38311726, 2024). "The multiplex immunofluorescence staining of GZMK in TPIT-lineage tumor cells also validate the existence of this cluster." (PMID 38167466, 2024). "Ti analysis showed that an increase of CD8 GZMK+ in tumor samples was a predictor of favorable GOLP response, and a higher post-to-pre GOLP ratio of CD8 GZMK+ was significantly correlated with more shrinkage of tumor (R = 0.92, P = 0.001)." (PMID 38245530, 2024). "Granzyme K (GZMK) is a crucial mediator released by immune cells to eliminate tumor cells, playing significant roles in inflammation and tumorigenesis." (PMID 38833021, 2024). "A sub-population of TPIT-lineage tumor cells highly expressing GZMK suggested a novel subtype of corticotroph tumors." (PMID 38167466, 2024). "We discovered that GZMK+ resting NK cells increased significantly in tumor tissues and were enriched in the tumor regions of both diseases." (PMID 39387546, 2024). "GZMK (formerly known as trypsin-2) is involved in one of the mechanisms by which cytotoxic T-lymphocytes and NK cells induce tumor cell apoptosis." (PMID 38464517, 2024). "PRF1, GZMA, and GZMK, 3 key effector molecules, were shown to be upregulated, and Rg1-pretreated T cells showed a stronger tumor lytic function at different effector: target cell ratios." (PMID 37546705, 2023). "Focusing on ICI-responsive GCs, we found a substantial proportion of pre-treatment ISG-15+CD8+ T clonotypes in effector T-cell populations (CXCL13+CD8+ T, ZNF683+ Tem and GZMK+ Tem) of post-treatment EBV (+) tumours." (PMID 37735150, 2023). "Specifically, we identified two CD8+ TEM clusters occupying a large proportion of CD8+ T cells, with T07 ANXA2+ TEM enriched in tumor sites and T08 GZMK+ TEM enriched in ascites." (PMID 37488416, 2023). "Previous have demonstrated that tissue resident CXCR6+ CD8 T cells are important components of tumor-infiltrating lymphocytes, which further evolve into GZMK+HAVCR2- subsets and terminally differentiated T cells." (PMID 37593098, 2023). "We obtained similar results when using human cells, with a greater increase in GZMK expression by CD8+ T cells induced by tumor-derived neutrophils compared to neutrophils from PB." (PMID 36347862, 2022). "In particular, CL12 included CD8+ T cells with negligible expression of GZMK and high levels of CD39, a marker that has been recently associated with tumor antigen encounters." (PMID 36347862, 2022). "As a consequence of the contact-mediated interaction with neutrophils, CD8+ T cells are skewed to produce high levels of GZMK, which in turn decreases E-cadherin on the intestinal epithelium and favors tumor progression." (PMID 36347862, 2022). "Specifically, different Vδ2+ cell phenotypes post-expansion preferentially produced either granzyme B or granzyme K in responses to tumour cell lines, differentially affecting their ability to lyse a range of tumour cell lines." (PMID 35404420, 2022). "Two effector CD4+ T cells, characterized by high expression of either IFNγ and TNF or GZMA and GZMK, showed an anti‐tumour function." (PMID 35184398, 2022). "Expanded TCRs in responders but not the non-responder showed upregulation of CD137 (TNSFR9, 4-1BB), a co-stimulatory molecule that interacts with antigen-presenting cells to support T cell anti-tumor activity and express GZMK." (PMID 34715028, 2021). "GZMK+ CD8+ T cells (cluster 2 in Tumor) represented an intermediate state between the effector and exhausted T cells." (PMID 33429363, 2021).
tumor (continued). "Consistently, pre-treatment tumor-infiltrating T cell clones predominantly adopt either exhausted, tissue-resident memory-like, or peripherally enriched GZMK+ progenitor states, implicating impaired intratumoral differentiation in limited anti-tumor immunity at baseline." (PMID 42000944, 2026). "The increased GzmK expression in the breast cancer tumor microenvironment (TME) corresponds to a high number of antitumor T cells, which is associated with increased overall survival (OS) and recurrence-free survival (RFS) of the patients and increased efficacy of cancer immunotherapy." (PMID 41009359, 2025). "Therefore, the accelerated accumulation of DN-Tem in patients is thought to occur, at least in part, through a continuous proliferation-independent differentiation from DP-Tem to GZMK+ DN-Tem during tumor progression." (PMID 40307573, 2025). "Two GZMK+ clusters, GZMK+ early-activation CD8 T cells and GZMK+ late-activation CD8 T cells, are also clonal, tumor-associated, and exhibit signatures that resemble an intermediate stage between activation and exhaustion, reflected by their intermediate level of TCF7 and CD27 expression." (PMID 40610460, 2025). "One critical observation from this study was the significantly remodelled CD8+ T cells activation and development in ICB‐resistant RCCs mediated by MARCO+ TAMs, resulting in significant reduction of tumor‐killing GZMK+CD8+ Tem cells as well as accumulation of tumor‐resident ZNF683+CD8+ Trm cells." (PMID 41117057, 2025). "Hence, further studies in several other cancers will establish GzmK’s role in tumor immunity, such as turning a cold tumor into a hot one or vice versa, and increasing the efficacy and responsiveness of immunotherapy among patients with cancer." (PMID 41009359, 2025). "Therefore, we evaluated the correlation between the cytotoxic scores of GZMK+T cells and the antigen presentation scores of DCs in tumor samples, and the results showed a significant positive correlation." (PMID 38311726, 2024). "The prevalence of this GZMK+ T cell subset suggests it may play a significant role in tumor immunity." (PMID 39026661, 2024). "It is an interesting finding that GZMK is highly expressed in a subpopulation of corticotroph tumor cells, and similar results could also be observed in the previous studies." (PMID 38167466, 2024). "We suspected that accelerating the migration of ascites-derived GZMK+ TEM cells into tumor sites could be a potential therapeutic strategy for OC." (PMID 37488416, 2023). "GZMK (Granzyme K) is a cytotoxic granule that promotes tumor death." (PMID 37189838, 2023). "We noted enrichment of LAG-3+GZMK+CD8+ T cells in pre-MGD013-treated tumours." (PMID 37735150, 2023). "Taken together, these findings provide insights into the cycle of CD8+ T cells in OC and suggest that ascites-derived GZMK+ TEM cells might serve as a direct source of tumor-infiltrating TEX cells." (PMID 37488416, 2023). "Moreover, cathepsin B+ tumor‐associated macrophages overactivates CD8+ T cells, leading to an enrichment of granzyme K+ senescent CD8+ T cells in MIA." (PMID 37991139, 2023). "Treatment of recGBM with neoadjuvant PD-1 checkpoint blockade improves survival outcomes by increasing anti-tumor T-cell responses, including GZMK; however, this is curtailed by additional T-cell checkpoints and other immunosuppressive pathways by the myeloid populations." (PMID 37189838, 2023). "The results indicated that ascites-derived GZMK+ TEM cells might serve as an important source of T cells infiltrating into tumor sites and further transit into TEX or ANXA2+ TEM." (PMID 37488416, 2023). "The pre-treatment tumour exhibited a significant infiltration of LAG-3+GZMK+ CD8+ T cells." (PMID 37735150, 2023).